BRCA2 (BRCA2 DNA repair associated)
Diseases named in the same sentence as BRCA2 in open-access papers (continued):
Sharing a sentence is not in itself a finding about the gene and the disease.
tumor (continued). "In our cohort, one patient, ACC-2, with a tumor harboring the loss-of-function mutation in BRCA2 developed multiple liver metastases but then experienced complete remission after receiving cisplatinum." (PMID 25743105, 2015). "Following clinical trials also provided proof of concept of olaparib single-agent activity of PARP inhibition in patients with tumours that have genetic loss of function of BRCA1-associated or BRCA2-associated DNA repair." (PMID 26610585, 2015). "One of these patients, ACC-2, whose tumor harbored the somatic frameshift mutation with loss of the wild-type allele of BRCA2, received cisplatinum after a recurrence, with liver metastasis and experienced complete remission of the recurring tumor." (PMID 25743105, 2015). "In this case, tumor sequencing led to the discovery of a pathogenic constitutional BRCA2 mutation, and a MLH1 alteration, initially misclassified as pathogenic, but later reinterpreted as a variant of uncertain significance." (PMID 25712765, 2015). "Hereditary defects in genes for HR factors such as BRCA1 and BRCA2 lead to cancer predisposition syndromes and tumours that are reliant on alternative repair pathways for survival." (PMID 25833379, 2015). "One of the key findings was the discovery of a potent and specific beneficial effect of PARP inhibition in BRCA2-deficient tumours, due to the defect in homologous recombination repair (HRR) in the BRCA2-deficient cells." (PMID 26339143, 2015). "Pre-clinical work demonstrated that these inhibitors cause synthetic lethality in tumour cells with BRCA1 or BRCA2 gene defects, an observation that has also been confirmed in clinical trials." (PMID 25883215, 2015). "BRCA1 and BRCA2 are tumor suppressor genes encoding proteins involved in a common pathway of DNA double-strand repair." (PMID 24959366, 2014). "BRCA1- and BRCA2-associated tumours showed few tandem duplications, indicating that the mechanisms responsible for chromosomal rearrangements in these tumours were distinct from those in triple-negative tumours, which exhibited tandem duplications." (PMID 24792170, 2014). "Tumour OESO_1636 displayed an unstable genome (776 SVs) and harboured a somatic nonsense BRCA2 mutation." (PMID 25351503, 2014). "Included in the list of genes affected by structural variants is BRCA2, a tumour suppressor gene encoding a protein that repairs double-stranded (ds)DNA breaks by homologous recombination." (PMID 24244370, 2013). "We have found positive BRCA1 protein nuclear staining in frozen and FFPE tumor and lactating tissue from a patient with a BRCA2 mutation." (PMID 23855721, 2013). "Immunohistochemical analysis of the BRCA2 mutated model demonstrated decreased tumor cell proliferation and increased numbers of dead cells following olaparib treatment, while wild-type tumor characteristics were not affected." (PMID 24363999, 2013). "Among these new compounds, PARP inhibitors have been shown to be highly lethal to tumor cells with deficiencies in DDR factors such as BRCA1 or BRCA2." (PMID 24252502, 2013). "Sensitization to radiation and alkylating agents was enhanced in DSB repair-deficient cells, consistent with the remarkable sensitivity to PARP inhibition of BRCA-1 and BRCA-2-deficient tumor cells." (PMID 23565244, 2013). "There was a significant positive association between PIK3CA mutation incidence and BRCACX (17.2%) compared with BRCA2 (0%) associated tumours (P = 0.030)." (PMID 23971979, 2013). "Mutations in BRCA1 and BRCA2 genes confer high lifetime risks of breast and ovarian cancer, among other neoplasias." (PMID 23613828, 2013). "Determination of the base sequence of BRCA2 in a tumor sample and of this sequence comparison with the BRCA2 consensus sequence is the most standard method for detecting mutations in tumor samples in humans." (PMID 22471976, 2012).
tumor (continued). "Some splicing variants of tumor suppressor genes (e.g., BRCA2) in tumor tissue have been associated with tumorigenesis because these splicing variants often lead to frameshift mutations." (PMID 22471976, 2012). "Despite extensive knowledge about female BRCA1, BRCA2 and other inherited familial breast tumours at present, little is know of male tumours from high-risk families." (PMID 23146383, 2012). "The aim of our study was to investigate the effect of regulatory genetic variation of the BRCA2 tumor suppressor gene on disease risk." (PMID 22513257, 2012). "Among new therapies that are under investigation, the most important one is PARP inhibition, which induces synthetic lethality in tumour cells deficient in homology-directed DNA double-strand break repair such as cells mutated in BRCA1 or BRCA2." (PMID 23110154, 2012). "BRCA2-associated tumours are also predominantly high-grade invasive ductal carcinomas of no special type but they often demonstrate a luminal phenotype despite their high histologic grade." (PMID 22053997, 2011). "Despite the great interest in BRCA2 function and its role in tumourigenesis and DNA repair, there are few tumour cell models of BRCA2 deficiency that can be used productively in the laboratory." (PMID 21750719, 2011). "The BRCA2-deficient tumour samples PD3689a and PD3690a have lower frequencies of indels flanked by homology, although it is possible that these rates are under-represented due to the low sequence depth used in their analysis." (PMID 21750719, 2011). "The compilation of such genomic datasets will undoubtedly underlie a greater understanding of this complex disease, and how loss of BRCA2 contributes to tumour progression." (PMID 21750719, 2011). "The results presented here demonstrate divergent paths of tumor evolution in BRCA2 carriers and that deletion of the wild-type BRCA2 allele, together with co-occurring changes at 6 q, 11 q, and 17 q, are important events in progression toward advanced disease." (PMID 21958427, 2011). "Adjusting for grade, BRCA2-associated tumours are more often ER-positive and are less likely, compared with controls, to express the basal cytokeratin CK5 or to overexpress HER2/neu protein." (PMID 22053997, 2011). "Here, loss of the BRCA2 wild-type allele occurs more frequently in the luminal subtype, where it correlates with increased tumor growth rates." (PMID 21958427, 2011). "The major strength of the current study is the large sample of BRCA1 and BRCA2 mutation carriers with SNP and tumour marker information." (PMID 22053997, 2011). "The observation that the incidence of small indels in the context of short regions of repetitive sequence occurs more frequently in Capan-1, and to some extent in the BRCA2 deficient tumours PD3689a and b, is intriguing." (PMID 21750719, 2011). "Although two BRCA2-deficient tumours have previously been assessed by massively parallel DNA sequencing, this was only at low depth, sufficient for studies of chromosomal rearrangements, but not SNPs and indels." (PMID 21750719, 2011). "In our mouse models, we find that BRCA1 and BRCA2 loss clearly have different impacts on tumor development." (PMID 20735817, 2010). "Loss of heterozygosity was tested for in the DNA of tumour tissue of the young-onset group by typing four microsatellite markers that flanked the BRCA2 gene, followed by sequencing." (PMID 20736950, 2010). "This is consistent with a tumour suppressor model and indicative of a causal relationship between BRCA2 germline mutations and predisposition to PrCa in these individuals." (PMID 20736950, 2010). "This work confirms the role of Brca2 as a tumour suppressor in the prostate and provides a model to test potential therapeutics in Brca2-deficient prostate neoplasia." (PMID 20585617, 2010). "This is what normally happens in most BRCA2-mutated tumour, where inactivation of the wild-type allele occurs by LOH, abolishing normal protein expression." (PMID 20877358, 2010).
tumor (continued). "As the majority of BRCA2-deficient cells, the tumour cells contain only the truncated BRCA2 protein, indicating that LOH has occurred as a consequence of an inactivating mutation in the second allele." (PMID 20877358, 2010). "We show that this xenograft accurately reflects the genetic and the phenotypic features of the primary tumour, thus providing a new model to test new therapies for BRCA2-mutated patients." (PMID 20877358, 2010). "A large difference was also seen between tumours from BRCA1 and BRCA2 mutation carriers with tumours from BRCA2 mutation carriers being significantly more methylated than tumours from BRCA1 mutation carriers." (PMID 20565864, 2010). "We have assessed survival in young PrCa cases with a germline mutation in BRCA2 and investigated loss of heterozygosity at BRCA2 in their tumours." (PMID 20736950, 2010). "In some cases, carrier mutation probabilities for BRCA2 are also altered when information on pathology of the tumour is available, because the BRCA1 and BRCA2 carrier probabilities are interdependent." (PMID 20482762, 2010). "Recently, inhibitors of the DNA repair proteins, poly(ADP-ribose) polymerase 1 and 2 (PARP1/2), have been shown to be selectively cytotoxic to tumour cells with BRCA1 or BRCA2 deficiency." (PMID 20877358, 2010). "Tumours from germline BRCA2 mutation carriers had a higher degree of CpG methylation as compared with BRCA1-mutated, other familial and sporadic tumours (P = 0.007, ANOVA)." (PMID 20565864, 2010). "Next, we identified syntenic CNAs that co-occurred in both the mouse and human BRCA1-mutated, BRCA2-mutated and control tumor groups." (PMID 20735817, 2010). "BRCA2 is thought to act as a tumour suppressor, with tumours arising from BRCA2 mutations frequently demonstrating loss-of-heterozygosity with loss of the wild-type allele." (PMID 20585617, 2010). "The probability that an individual carries a BRCA1 or BRCA2 mutation given their family history and tumour marker status of family members was computed in sample pedigrees." (PMID 20482762, 2010). "The clinical sample and the xenograft tumours present some of the chromosome alterations that have already been frequently described in the genomic profiles of BRCA2-mutated tumours, as gains of 8q and 20q, and loss of 13q." (PMID 20877358, 2010). "Similar to this case, in MZ twins with mutations in BRCA1 and BRCA2 tumours were detected at the same approximate location and same age." (PMID 20687928, 2010). "DNA sequencing of the primary tumour, and P0 and P8 from the HBCx-17 xenograft showed the presence of the germline BRCA2 mutation identified in the patient (c.6033_6034delTT; p.Ser2012GlnfsX5)." (PMID 20877358, 2010). "Another GII-high subgroup (n = 9) was highly enriched of tumours derived from BRCA2 germline mutation carriers (8 of 9; Fisher's exact test P < 10-4)." (PMID 19589159, 2009). "The BRCA1 and BRCA2 human tumour suppressor genes are deficient in a subset of breast, ovarian and prostate cancers, and are normally required (among their other roles) for DSB repair by HR." (PMID 19319136, 2009). "Tumours derived from BRCA2 germline mutation carriers have previously been shown to primarily display luminal phenotypes and rarely overexpress HER-2 gene products and these findings were confirmed here." (PMID 19589159, 2009). "This suggests similarities in the mechanisms promoting genomic instability for BRCA1- and BRCA2-associated tumours, possibly relating to deficiency in DNA repair through homologous recombination." (PMID 19589159, 2009).
tumor (continued). "Tumours derived from BRCA1 or BRCA2 germline mutation carriers have generally lost the wild-type BRCA1 or BRCA2 alleles, respectively." (PMID 19589159, 2009). "AI at the BRCA1 locus was found to be strongly associated with AI at the BRCA2 locus (P < 0.0001, OR = 7.0, 95%CI = 3.0–16.4) with 26 of 124 (21.0%) informative tumours having AI at both loci." (PMID 16846527, 2006). "Among BRCA2-associated tumours, a slight increase has been observed in the incidence of lobular or tubulolobular carcinomas." (PMID 15642173, 2005). "They found that the gene expression profiles of the three tumour groups differed significantly from each other, underscoring the fundamental differences between BRCA1 and BRCA2 mutation-associated tumours." (PMID 15714204, 2005). "We performed the analysis of BRCA1 and BRCA2 genes in 14 women with this histological tumor subtype and found three truncating mutations (21.4%) in exon 11 of the BRCA1 gene." (PMID 16168118, 2005). "The breast – stomach phenotype is one of several types of familial tumour aggregation at varying sites associated with BRCA2 gene mutations." (PMID 12373604, 2002). "Combined allelic loss of both BRCA1 and BRCA2 gene was seen in 12 of the 17 (71%) informative hereditary tumours, whereas copy number losses of both BRCA genes was seen in only 4/14 (29%) sporadic control tumours studied by FISH." (PMID 11710835, 2001). "Still, there is growing interest in understanding how these common variants might influence BRCA2 function, modify tumor behavior, or shift the age of onset." (PMID 40843725, 2025). "Notably, two patients (IDs 13 and 118) harbored tumor BRCA2 pathogenic variants at low VAF, alongside with pathogenic alterations in mismatch repair (MMR) genes, and both were MSI-high on subsequent analysis." (PMID 41465396, 2025). "Targeting PIF1 by chemical inhibition or genetic modification in BRCA2-deficient MBs could allow for selective killing of tumor cells, sparing surrounding normal cerebellum that lacks Pif1 expression." (PMID 40854122, 2025). "Subsequent molecular profiling of the tumor tissue revealed a heterozygous BRCA2 mutation." (PMID 40978059, 2025). "Instead, the dog had a BRCA2 gene mutation, known for roles in DNA repair and tumor suppression." (PMID 40723533, 2025). "Next-generation sequencing analysis of the locally recurrent tumor as well as the pleural metastasis revealed a BRCA2 mutation in exon 11 (p.N1279S), which was somatic, given that germline testing for BRCA1 and BRCA2 revealed no mutations in either of these genes." (PMID 39392573, 2025). "Similarly, ATR inhibition potentiates the cytotoxicity of PARP inhibitors in certain BRCA2-mutated tumor cells." (PMID 41373774, 2025). "In addition, responses to poly-adenosine diphosphate-ribose polymerase inhibitors (PARPi) have been associated with homozygous BRCA2 somatic loss in the primary tumor." (PMID 39937427, 2025). "The same BRCA2 variant was detected in both the tumor and germline samples from this patient." (PMID 41008914, 2025). "Further research in PCMC is needed to better understand this uncommon tumor and whether a BRCA2 mutation could contribute to increased PCMC metastatic potential." (PMID 40225096, 2025).
tumor (continued). "Moreover, the broader range of functions of BRCA1 implies that it is the more critical counterpart of the two BRCA genes, with more severe genotoxicity found in tumours associated with faulty BRCA1 than defective BRCA2." (PMID 40429877, 2025). "To directly test whether uracil accumulation occurs on ssDNA, we treated BRCA2-deficient cells and BRCA2 mutant tumor cells (PEO1) with S1 nuclease, which degrades ssDNA." (PMID 41162355, 2025). "Low expression of BRCA2 was also observed in the tumor suggesting loss of BRCA2 function." (PMID 40072012, 2025). "The loss of BRCA1 and BRCA2 leads to the impairment of homologous recombination repair functions, rendering tumor cells unable to effectively repair DNA damage, consequently causing genomic instability and tumor progression." (PMID 40370464, 2025). "In BRCA1/BRCA2-deficient tumor cells, the HR pathway is aberrant." (PMID 39885134, 2025). "Prostate-specific antigen monitoring for men with pathogenic BRCA2 variants, testicular ultrasound and tumor marker evaluation for men at high risk of testicular cancer, and hematological evaluations for those with severe spermatogenic failure and inexplicable systemic symptoms are a few examples." (PMID 41296434, 2025). "Since PARPis and PP2Ais target the 2 different mechanisms of DNA damage repair defects and SAC activation silencing in BRCA2-deficient tumor cells, we speculated that the combined use of PARPi and PP2Ai should have prominent advantages." (PMID 37934606, 2024). "Compared with BRCA1-deficient tumors, BRCA2-deficient tumors have a greater abundance of genes expressing innate and acquired immunity and a greater population of macrophages, natural killer cells, T cells, and dendritic cells in the tumor microenvironment." (PMID 38184581, 2024). "The second variant, BRCA2 p.Q2009Afs*8 was found in one patient with a HER2+ tumor (3%)." (PMID 39264897, 2024). "Panel testing allows for the screening of multiple genes beyond BRCA1 and BRCA2 that may be associated with tumor development and/or treatment response." (PMID 39237557, 2024). "Our results reveal that reducing AURKB levels is the key to reversing the growth inhibition caused by BRCA2 deficiency–induced K-fiber instability and SAC activation, so how to reactivate the recognition of deficient K-fibers and ultimately kill BRCA2-deficient tumor cells is a very important issue." (PMID 37934606, 2024). "As a result, PP2A may be an exciting potential synthetic lethal target for BRCA2-deficient tumor cells." (PMID 37934606, 2024). "One 30-year-old patient with a family history of BC (HT163B1) has a germline frameshift variant of unknown significance (p.Y1672fs) in BRCA2 that has significant loss of heterozygosity in the tumor (FDR = 0.0001)." (PMID 39478117, 2024). "However, the full tumour spectrum associated with BRCA2 mutations, particularly in patients with other concurrent pathogenetic mutations, is unexplored." (PMID 39702187, 2024). "Therefore, a correlation between the variant localization in the BCCRs of BRCA2 and type of tumor was observed in 50% (8/16) of BRCA2-positive MBC patients." (PMID 38974244, 2024). "BRCA1 and/or BRCA2 gene mutations have since been shown to play a role in many more tumor types." (PMID 38540206, 2024). "BRCA1 and BRCA2 genes are typically classified among DNA repair genes, playing a regulatory role in the cell cycle by encoding proteins involved in responding to DNA damage, and hence, acting as tumour suppressor genes." (PMID 39594243, 2024). "Again, data analysis showed a BRCA2 loss, and the tumor cell content was 85%." (PMID 39363506, 2024). "Hence, the increased dependence of PARG;BRCA2-deficient cells on EXO1/FEN1 function is also relevant in human tumor cells." (PMID 38360994, 2024).